EZH2 (enhancer of zeste 2 polycomb repressive complex 2 subunit)
Diseases named in the same sentence as EZH2 in open-access papers (continued):
Sharing a sentence is not in itself a finding about the gene and the disease.
breast cancer (continued). "The combined genotype of EZH2 rs12670401 (TC + CC) and EZH2 rs6464926 (CT + TT) was significantly associated with the susceptibility to breast cancer (OR =1.465, 95% CI: 1.055–2.036, P=0.022)." (PMID 29089464, 2018). "EZH2 rs12670401, EZH2 rs6464926, age of menarche, and menopausal status were associated with breast cancer susceptibility." (PMID 29089464, 2018). "The interaction mechanism of EZH2 rs12670401 and EZH2 rs6464926 polymorphisms in the development and progression of breast cancer is needed to be further studied in the future." (PMID 29089464, 2018). "In breast cancer, Ezh2 overexpression is associated with aggressive breast cancers and poor prognosis and inversely correlated with H3K27me3 expression." (PMID 30080881, 2018). "In some cancers, such as human breast cancer, lung cancer and digestive cancers, the overexpression of EZH2 proteins have been associated with the poor prognosis of the malignancies." (PMID 30542123, 2018). "The mechanism underlying the inhibition of EZH2 by DZNepA communicates the involvement of other methyltransferases in NIC-mediated increased breast cancer risk, which needs further investigation." (PMID 29396474, 2018). "In these women, >20% epithelial expression of EZH2 was associated with a 3.15-fold increase in breast cancer risk (OR = 3.15, 95% CI 1.39–7.14), relative to women with <10% expression of EZH2." (PMID 28253895, 2017). "There was also a 1.22-fold increased risk of breast cancer per 5% increase in epithelial EZH2 expression (OR = 1.22, 95% CI 1.06–1.41)." (PMID 28253895, 2017). "More relevant to this study, the expression and prognostic significance of EZH2 has been extensively investigated and in breast cancer it is now generally accepted to be associated with a worse prognosis." (PMID 28253895, 2017). "Individuals with high epithelial EZH2 and lower ER expression had a fourfold increased risk of breast cancer development (OR = 4.02, 95% CI = 1.29 –12.59) compared with those who had low EZH2 and ER expression." (PMID 28253895, 2017). "In breast cancer, increased EZH2 expression is associated with aggressiveness and has been suggested to identify normal breast epithelium at increased risk of breast cancer development." (PMID 28253895, 2017). "The risk of developing breast cancer increased for each 5% increase in EZH2 expression (OR 1.22, 95% CI 1.02–1.46, p value 0.026)." (PMID 28253895, 2017). "The overexpression of EZH2 is strongly associated with the development of breast cancer and breast cancer’s aggressiveness." (PMID 28933369, 2017). "We examined the association between EZH2 protein expression and subsequent breast cancer risk using logistic regression in a nested case-control study of benign breast disease (BBD) and breast cancer within the Nurses’ Health Studies." (PMID 28253895, 2017). "In conclusion, the currently available evidence suggests EZH2 expression in the normal breast can be used as a biomarker of breast cancer risk." (PMID 28253895, 2017). "In utero BPA exposure has been shown to increase risk of prostate and breast cancer later during adulthood by altering DNA methylation in progenitor cells, and increasing EZH2 in mammary glands." (PMID 29027980, 2017). "On its own, EZH2 expression in >20% of the normal breast epithelial cells was associated with a threefold increased risk of breast cancer, and a fourfold increased risk if there is concomitant low ER expression." (PMID 28253895, 2017). "We found that EZH2 expression in normal breast epithelium was associated with breast cancer risk, particularly when >20% of the epithelial cells expressed EZH2." (PMID 28253895, 2017). "This is the first study, to our knowledge, to directly examine the independent association between EZH2 expression in the normal breast and risk of breast cancer, in a large prospective study." (PMID 28253895, 2017).
breast cancer (continued). "Two prior studies have analyzed EZH2 expression in normal breast and BBD lesions with the goal of establishing EZH2 as a potential marker of breast cancer risk." (PMID 28253895, 2017). "In our secondary analysis, we found that the expression of ER appeared to modulate the effect of EZH2 on breast cancer risk." (PMID 28253895, 2017). "EZH2 is associated with transcriptional repression in breast cancer and, therefore, we examined the ZLD1039-induced gene-expression changes in MCF-7 cells using gene expression arrays." (PMID 26868841, 2016). "The results showed that high EZH2 expression was associated with poor OS in breast cancer instead of lung and CRC." (PMID 26683709, 2016). "The association of both FOXO3 and EZH2 mRNA levels in survival analyses provides further evidence for the involvement of both genes in breast cancer progression." (PMID 27043660, 2016). "Together, these data support the idea that EZH2 negatively regulates FOXO3 transcription in BRCA1-deficient breast cancer cells, whereas this EZH2 activity is repressed by BRCA1 in BRCA1-competent cells." (PMID 27043660, 2016). "Its overexpression was first associated with amplification at 7q35 (more than four EZH2 copies per cell) in approximately 15 % of the 225 analyzed breast cancers (BCs)." (PMID 27239242, 2016). "Evidence has shown that EZH2 is highly expressed in many types of solid tumors, including breast cancer, and its higher expression is associated with aggressive disease and poor outcome." (PMID 27494834, 2016). "A correlation between loss of differentiation and deregulated expression of EZH2 has also been proposed in human breast cancer." (PMID 27502594, 2016). "In breast cancer, several lines of evidence have implicated overexpression of EZH2 and repression of tumor suppressors such as KRT5, KRT6, CDH3, RAD51 paralogs, CDKN1C, FOXC1, Wnt/β-catenin signaling (c-Myc, Cyclin D1, Axin2), RKIP and KLF2." (PMID 27835578, 2016). "In humans, EZH2 is linked to oncogenic function in several carcinomas, including breast cancer, and dysregulation of EZH2 has been particularly associated with loss of differentiation and the development of poorly differentiated breast cancer." (PMID 27502594, 2016). "This larger dataset also uncovered significant prognostic value associated with PRMT8 and SIN3A as well as confirmed the well-known association of high EZH2 expression levels with poor survival in breast cancer." (PMID 27863398, 2016). "Retrospective studies from clinical breast cancer patients indicate that high expression of EZH2 is associated with short survival." (PMID 27517917, 2016). "Some groups have reported an increase in the transcriptional levels of EZH2 (a H3K27 histone methyl-transferase) in the luminal breast cancer subtype, and an association between increased EZH2 activity and poor prognosis has been reported." (PMID 27386402, 2016). "While deposition of H3K27me3 by EZH2 enzyme is often increased in aggressive breast cancers, and mutation in the H3K27me3 demethylase KDM6A are common in renal cell carcinoma." (PMID 26840455, 2016). "Overexpression of EZH2 which is responsible for H3K27 methylation, in prostate and breast cancer, was found to be associated with poor prognosis, suggestive of EZH2 being an oncogene." (PMID 27119045, 2016). "The overexpression of EZH2 was first found to be associated with carcinogenesis in prostate cancer and breast cancer by microarray studies." (PMID 27092879, 2016). "Consistently, high FOXO3 and EZH2 mRNA levels were significantly associated with good and poor prognosis in breast cancer, respectively." (PMID 27043660, 2016). "Overexpression of EZH2 is associated with progression of various tumors, including prostate and breast cancers." (PMID 26038315, 2015). "EZH2 overexpression has been linked to poor prognosis and shown to be a marker of aggressive breast cancer, associated with difficult-to-treat basal or triple negative breast cancer." (PMID 26300989, 2015).
breast cancer (continued). "Inspired by these achievements, two different L-DNAs corresponding to EZH2 encoding messenger RNA and microRNA 21 (termed miRNA21) were tested as specific breast cancer markers." (PMID 26634810, 2015). "We next assessed alterations of EZH2 or other genes encoding core PRC2 components by targeted sequencing in breast cancer metastases previously analyzed by Affymetrix CytoScan arrays." (PMID 26637281, 2015). "Tissue microarray analysis revealed that EZH2 protein levels were strongly associated with breast cancer aggressiveness." (PMID 25537518, 2015). "Consistent with this, one study showed that EZH2 was regulated by a novel signaling network including SP proteins in breast cancer cells and associated with poor survival of breast cancer patients." (PMID 26362062, 2015). "Consistently, when corrected for proliferation, the prognostic value of EZH2 expression is inverted; low EZH2 expression relative to proliferation is associated with poor prognosis in breast cancer." (PMID 26637281, 2015). "Tissue microarray analysis demonstrated that EZH2 protein levels were strongly associated with aggressiveness of breast cancer." (PMID 26378045, 2015). "Recently, loss of BRCA1 function was shown to be associated with the expansion of breast cancer stem and progenitor cells, conferring a dependency on the expression of the polycomb repressor 2 complex protein EZH2." (PMID 25026298, 2014). "In a recent study, EZH2 expression was associated with Ki-67 in endometrium, prostate, and breast cancer." (PMID 24312307, 2013). "Functions associated with increased expression of EZH2, like invasive growth in prostate and breast cancer as well as endometrial carcinoma point to its role in endometrium proliferation early in the estrous cycle." (PMID 22952593, 2012). "In breast carcinoma, EZH2 protein levels have been found to be strongly associated with poor clinical outcomes." (PMID 23133536, 2012). "Under diagnostic aspects, it is noteworthy that upregulation of EZH2 expression can be detected very early in breast cancer development, even before atypic cells are histologically evident." (PMID 20920340, 2010). "Other chromatin modifying repressor proteins, including the MTA components of the Mi-2/NuRD complex and EZH2, are also associated with breast cancer growth and progression." (PMID 20920219, 2010). "Overexpression of EZH2 protein has been shown in several carcinomas, and has been associated with increased tumour cell proliferation and worse outcome in breast cancer, melanomas, endometrial carcinomas, and also in hormone-refractory prostate cancer." (PMID 19773751, 2009). "Gene expression analysis demonstrated that EZH2 is overexpressed in BRCA1-deficient mouse mammary tumors." (PMID 19709408, 2009). "Tumors from BRCA1-mutation carriers belong to this group of aggressive breast cancer, and accordingly EZH2 mRNA levels are also high in human BRCA1-deficient tumors." (PMID 19709408, 2009). "The association between proliferation and EZH2 expression has been shown in other malignancies such as breast cancer and melanomas." (PMID 19773751, 2009). "We demonstrate by specific knock-down experiments that EZH2 overexpression is functionally relevant in BRCA1-deficient breast cancer cells." (PMID 19709408, 2009). "We evaluated the association between BMI1 or EZH2 expression and overall survival among 295 breast cancer patients." (PMID 19099573, 2008). "Subsequently, it was shown that EZH2 overexpression was associated with the aggressivenessof breast cancer." (PMID 16638127, 2006). "Overexpression of EZH2 is associated with progression of prostate cancer and aggressiveness of breast cancer." (PMID 16638127, 2006).
breast cancer (continued). "Furthermore, we discuss emerging therapeutic strategies for KMT2C-deficient breast cancers, such as epigenetic modulators (EZH2 inhibitors, KDM6A inhibitors, and BET inhibitors), DNA damage response (DDR)-targeting agents, and pathway-specific inhibitors." (PMID 41674102, 2026). "Overexpression of EZH2 is associated with poor prognosis in breast cancer." (PMID 40584614, 2025). "Additionally, EZH2, which is a transcriptional repressor and a histone methyltransferase, plays a role in cell cycle regulation and is associated with aggressive breast cancer." (PMID 39744000, 2024). "Moreover, a potential association was discovered between HCMV, PGCCs, and EZH2, as well as their potential interaction with Myc in the context of breast cancer development." (PMID 39205199, 2024). "EZH2 can inhibit the transcription of tumor suppressor genes, and EZH2 overexpression or activation mutation is found in a variety of malignant tumors except melanoma, such as breast cancer, prostate cancer, uterine cancer, gastric cancer, and nuclear renal cell carcinoma." (PMID 38773600, 2024). "Finally, a recent report has indicated another cytoplasmic role for EZH2 linked to breast cancer metastasis." (PMID 37491334, 2023). "We therefore aimed to identify synthetic lethal partners of EZH2 in BRCA1-deficient breast cancer." (PMID 35715861, 2022). "Effective in vivo anti-tumor activity of combined GSK126 and cisplatin treatment also enhanced overall survival of mice bearing BRCA1-deficient mouse mammary tumors, suggesting that EZH2 inhibition enhances the sensitivity to platinum drugs in EZH2-overexpressing breast tumors." (PMID 35715861, 2022). "As a consequence, one can believe that targets EZH2 in breast cancer patients with ARID1A mutations might be a promising treatment option." (PMID 36212140, 2022). "Elevated EZH2 levels in breast cancer are associated with poor prognosis." (PMID 35137163, 2022). "Here, the association of EZH2 mRNA expression with BRCA1-mutant breast cancer was further evaluated using the TCGA BRCA whole exome sequencing data set (n = 526) confirming the increased expression of EZH2 in BRCA1-mutant (n = 18), compared to BRCA1-wild type breast cancer (n = 508) (p = 0.0003)." (PMID 35715861, 2022). "Taken all these results into consideration, VEGFA and EZH2 might be the most potential targets involved in the established m5C regulators-associated miRNA–mRNA network in breast cancer." (PMID 35812757, 2022). "Notably, high level of EZH2 is implicated in tumorigenesis and correlates with poor prognosis in various tumor types, including breast cancer, ovarian cancer, etc.." (PMID 36038549, 2022). "However, Mittal’s group has performed the bioinformatics analysis of epigenetic-associated genes in breast cancer patients, which characterized overexpression of EZH2 catalytic function as a predominant carrier in TNBC metastasis with poor overall survival." (PMID 36446780, 2022). "Moreover, expression correlation analysis suggested that DNMT3B was markedly positively associated with VEGFA and EZH2 in breast cancer." (PMID 35812757, 2022). "EZH2 overexpression is associated with instability of ribosomal DNA and an increase in ribosome synthesis that is in favor of increasing proliferation and invasion of breast cancer cells." (PMID 35236381, 2022). "Just as EZH2 has been recognized as a marker of aggressive breast cancer and is associated with poor survival, downregulation of EZH2 decreases the growth and metastasis of invasive breast carcinoma, but EZH2 inhibitors alone have shown little benefit against breast cancer." (PMID 36038549, 2022).
breast cancer (continued). "The ability of combined EZH2/ATM inhibition to propagate DNA damage in BRCA1-deficient breast cancer could enhance the response to immuno-oncological treatment." (PMID 35715861, 2022). "To investigate whether combined EZH2/ATM inhibition induces apoptosis in BRCA1-deficient mouse mammary tumor cells, we measured the percentage of Annexin V/propidium iodide double-positive cells by flow-cytometry." (PMID 35715861, 2022). "Increased expression of EZH2 transforms normal breast epithelial cells, is a marker of aggressive breast cancer, and associates with poor prognosis and EZH2 has been shown to expand stem cell populations in breast cancer though activation of the NOTCH1 pathway." (PMID 33750924, 2021). "Other alterations in the epigenome have been described in MCF-7 cells in mice exposed in utero to DES, such as the increase of the Enhancer of Zeste Homolog 2 (EZH2), a histone methyltransferase that has been linked to breast cancer risk, and the increase in Histone H3 trimethylation." (PMID 34639609, 2021). "YY1-mediated EZH2 activity is essential to gene expression; thus, we predicted that disruption of their interaction could cause perturbation in breast cancer cells and thus inhibit cancer progression." (PMID 34065631, 2021). "Indeed, the expression levels of PRMT1 and the methylation levels of the Arg342 residue of EZH2 correlate with poor clinical outcomes in breast cancer patients, suggesting the utility of PRMT1 as a diagnostic marker and therapeutic target for cancer." (PMID 34006904, 2021). "Elevated expression of EZH2 is seen in breast cancers and has been linked to poor prognosis." (PMID 33235291, 2021). "Some of the first evidence that BPA-induced epigenetic changes affect breast cancer pathogenesis was provided by the finding that treatment of MCF-7 cells with BPA increases mRNA and protein expression of EZH2, a histone methyltransferase linked to breast cancer risk." (PMID 32796699, 2020). "Moreover, additional investigators have found that higher EZH2 levels are independently associated with worse 5-year overall and disease-free survival in a large series of 410 breast cancer cases." (PMID 33050946, 2020). "On the other hand, EZH2 protein levels were strongly associated with breast cancer aggressiveness." (PMID 33330073, 2020). "The results showed that macrophage infiltration was positively correlated with EZH2 and LOXL4 expression, implying that tumor-associated macrophages (TAM) may play a vital role in EZH2/LOXL4-mediated progression of breast cancer." (PMID 32754259, 2020). "Similarly, lncRNA NEAT1 is expressed at significantly high levels in tissues and cell lines of breast cancer, and its knockdown caused a decrease in cell proliferation and EZH2 expression." (PMID 32157157, 2020). "Since DNA and histone hypermethylation has been linked to carcinogenesis, and the overexpression of EZH2 was found in numerous cancer forms, including breast cancer, prostate cancer, leukemia and pancreatic tumors, this has been considered to be a potential cancer therapy target." (PMID 33040049, 2020). "Aberrant PRC2 activity, sometimes caused by EZH2 mutations, is frequently associated with poor prognosis in hematological, lung, prostate, and breast cancer, and several small molecule inhibitors of EZH2 have recently been developed, including some currently evaluated in clinical trials." (PMID 31817960, 2019). "Overall, in this study we validate six direct targets of EZH2 associated with patient survival, in breast cancer using published datasets and corroborate the existing co-relation between them in human primary breast carcinoma along with their adjacent normal tissues." (PMID 30760814, 2019). "In different studies, overexpression of EZH2 has been identified as a biomarker of aggressive and highly proliferating tumors and is, hence, being associated with worse patient outcome, e.g., in endometrial, prostate, and breast cancer as well as melanoma." (PMID 31317325, 2019).